MSH6 (mutS homolog 6)
Diseases named in the same sentence as MSH6 in open-access papers (continued):
Sharing a sentence is not in itself a finding about the gene and the disease.
Lynch syndrome (continued). "Inactivating mutations in MSH6, a DNA MMR gene, are associated with Lynch syndrome." (PMID 37910143, 2023).
Lynch syndrome (continued). "Additionally, we observed mutations in the MSH6 and MLH1 genes that, with the patient’s family history of cancer, led us to strongly suspect the presence of Lynch syndrome." (PMID 37086325, 2023). "The case was reinterpreted as a patient with Lynch syndrome, and a MSH6 germline mutation, and two non-pathogenic POLE mutations, not included in the list of mutations identifiable by the test." (PMID 37874375, 2023). "However, MSH6 is the gene most commonly affected in those with Lynch syndrome and therefore, the higher proportion of germline path_MSH6 in OC simply reflects its prevalence in those with Lynch syndrome." (PMID 35792468, 2022).
Lynch syndrome (continued). "Loss of nuclear expression of MSH6 suggested a high probability of Lynch syndrome, in the absence of a previous family history of colorectal cancer." (PMID 33541411, 2021). "Moreover, it must be considered that most of our participants were Dutch, and the path_MSH6 rate of 30% among the Dutch LS registry patients was relatively high compared with the overall Prospective Lynch Syndrome Database." (PMID 33693762, 2021). "Therefore, the use of only two antibodies, anti-PMS2 and anti-MSH6 antibodies, allows the screening of Lynch syndrome to be performed with a sensitivity equivalent to that using four antibodies." (PMID 34185173, 2021). "The findings in MSH6 and PMS2 are of particular clinical importance, as these data are extremely limited in the literature until recently, yet clinicians counsel about a general increased risk for ovarian cancer with PVs in Lynch syndrome genes." (PMID 31406321, 2020). "Furthermore, the mutS homolog 6 (MSH6) and homolog 2 mismatch repair system component (PMS2) genes, apart of Lynch syndrome, increase patients' susceptibility for simultaneous diagnoses." (PMID 31183268, 2019). "We presented a case with similar features but showing only one identified germline MSH6 nonsense variant, diagnostic of Lynch syndrome and not the suspected CMMRD." (PMID 31604779, 2019).
Lynch syndrome (continued). "As the mismatch repair genes that are associated with Lynch syndrome include MLH1 or MSH6, but not MLH6, a query was sent to the insurer via the FSC." (PMID 29891881, 2018). "Again, the co-occurrence of this pathogenic mutation with p.T767I in MSH6, the loss of MSH6 protein expression and other factors provided evidence to upgrade this VUS to a likely pathogenic variant and the diagnosis was upgraded to Lynch syndrome." (PMID 29755653, 2018).
Lynch syndrome (continued). "Hereditary nonpolyposis colorectal cancer (Lynch syndrome) is caused by heterozygous germline mutations in MMR genes (including MSH6)." (PMID 25329635, 2014). "MSH6 is also recognized as a frequent cause of atypical Lynch syndrome (i.e., not fulfilling the Amsterdam criteria)." (PMID 24978665, 2014). "The clinical utility of Lynch syndrome testing for the index case depends on her age and the MMR gene mutated: the net benefit is lower for those diagnosed at older ages and with less-penetrant MSH6 mutations." (PMID 24056992, 2013). "We also found that the pattern of MMR deficiency in early-onset CRC patients is not identical to that for all Lynch syndrome cases, and is characterized by in increased frequency of MSH6 and PMS2 deficiency." (PMID 23049789, 2012). "Notwithstanding, some information is available with respect to the frequency of MSH6 and PMS2 mutations but there is relatively limited information available regarding the spectrum of disease, especially in Australian Lynch syndrome families harbouring deleterious changes in one of these two genes." (PMID 20487569, 2010). "Pathologists and clinicians should be aware that germline MSH6 variant carriers often present with minimal shift patterns and recognize that discordant cases (isolated loss of MSH6 without MSI-H) represent an essential step in the genetic diagnosis of Lynch syndrome." (PMID 41041321, 2025). "Delayed oophorectomy also may currently be taken into consideration in the case of other gene mutations predisposing patients to gynecological malignancies, such as MLH1, MSH6, and PMS2 in Lynch syndrome and PALB2, whose cancer risk range estimates overlap with BRCA." (PMID 36835955, 2023).